FGF23 (fibroblast growth factor 23)
Diseases named in the same sentence as FGF23 in open-access papers (continued):
Sharing a sentence is not in itself a finding about the gene and the disease.
X-linked hypophosphatemia (continued). "Loss of PHEX activity elevates plasma FGF23 levels, as typical of X-linked hypophosphatemia (XLH)." (PMID 35084563, 2022). "X-linked hypophosphatemia (XLH) is a rare, lifelong, progressive disease caused by a defect in the PHEX gene, leading to excessive levels of circulating FGF23 with a prevalence rate of around 1 in 20,000." (PMID 32162120, 2020). "To note, in a phase I clinical trial, administration of various amounts of anti-FGF23 antibodies increased tubular maximum transport of phosphate per glomerular filtration rate (TmP/GFR) in adult patients with X-linked hypophosphatemia (XLH)." (PMID 30820831, 2019). "Fibroblast growth factor 23 (FGF23) has first been described in context with the following orphan diseases: tumor induced osteomalacia, X-linked hypophosphatemia, and autosomal dominant hypophosphatemic rickets (ADHR)." (PMID 26491212, 2015). "Finally, we assessed the cardiovascular effects of chronically elevated endogenous Fgf23 in Hyp mice, a model of human X-linked hypophosphatemia (XLH)." (PMID 24797667, 2014). "X-linked hypophosphatemia (XLH) is a rare genetic disorder caused by an inactivating mutation in the phosphate-regulating endopeptidase X-linked (PHEX) gene, resulting in elevated levels of the hormone fibroblast growth factor-23 (FGF23)." (PMID 40060917, 2025). "The genetic basis of X-linked hypophosphatemia is a loss-of-function mutation in the PHEX gene (Phosphate regulating gene with Homology to Endopeptidases on the X chromosome), which leads to an enhanced production of phosphaturic hormone FGF23." (PMID 36847234, 2023). "X-linked hypophosphatemia (XLH), is a disorder that involves a mutation in the Phosphate Regulating Endopeptidase Homolog X-Linked (PHEX) gene, leading to an overexpression of FGF23." (PMID 35899095, 2022). "X-linked hypophosphatemia [XLH; OMIM (Online Mendelian Inheritance in Man) # 307800; incidence, 3.9 of 100,000 births] is the most common form of genetic rickets associated with increased levels of circulating fibroblast growth factor 23 (FGF23)." (PMID 34705504, 2021). "In these studies, patients with osteomalacia/hypophosphatemic rickets and animal models with X-linked hypophosphatemia display high serum FGF23 levels, but no cardiac remodeling." (PMID 31698866, 2019). "X-linked hypophosphatemia (XLH) is a rare, genetic, progressive, lifelong phosphate-wasting disorder caused by loss-of-function mutations in the PHEX (phosphate-regulating endopeptidase homologue, X-linked) gene, leading to excess circulating levels of fibroblast growth factor 23 (FGF23)." (PMID 39679164, 2025). "X-linked hypophosphatemia (XLH) is a chronic disabling hereditary musculoskeletal disorder associated with inactivating PHEX mutations and elevated circulating FGF-23 concentrations." (PMID 41445548, 2025). "X-linked hypophosphatemia (XLH) is a rare, genetic, progressive, lifelong disorder caused by pathogenic variants in the phosphate-regulating endopeptidase homolog, X-linked (PHEX) gene, resulting in excess fibroblast growth factor 23 (FGF23) and consequent renal phosphate wasting." (PMID 40260280, 2025). "X-linked hypophosphatemia (XLH), caused by mutations in the PHEX gene, disrupts FGF23-mediated phosphate regulation, thereby increasing the risk of OPLL." (PMID 40535334, 2025). "X-linked hypophosphatemia (XLH) is caused by an inactivating mutation in the phosphate-regulating endopeptidase X-linked (PHEX) gene whose defective product fails to control phosphatonin fibroblast growth factor 23 (FGF23) serum levels." (PMID 38818505, 2024). "Burosumab, an FGF23 targeting monoclonal antibody, was approved by the FDA in 2018 for use in children and adults with X-linked hypophosphatemia (or XLH)." (PMID 36042241, 2022).
X-linked hypophosphatemia (continued). "Supporting the notion that there are multiple pathways involved in FGF-23 upregulation beyond phosphate sensing or HIF1α, conditional deletion of HIFα (HIF1α/Osteocalcin (OCN)-Cre) does not reduce FGF-23 levels in the Hyp mice, an animal model of X-linked hypophosphatemia (XLH)." (PMID 36246903, 2022). "This assumption is consistent with studies in murine models of X-linked hypophosphatemia that could not detect a pathological cardiac phenotype despite markedly elevated Fgf23." (PMID 34778257, 2021). "Moreover, FGF23 excess also leads to several congenital hypophosphatemic diseases, such as autosomal dominant hypophosphatemic rickets (ADHR: OMIM #193100) and X-linked hypophosphatemia (XLH; OMIM #307800)." (PMID 30627598, 2019). "Kyowa Hakko Kirin (KHK) of Japan collaborated with Ultragenyx to develop humanized recombinant human FGF23 monoclonal antibody, KRN23, for the treatment of X-linked hypophosphatemia (XLH), a rare metabolic bone disorder." (PMID 29949887, 2018). "The genetic disorders X-linked hypophosphatemia (XLH), autosomal dominant hypophosphatemic rickets (ADHR), and autosomal recessive hypophosphatemic rickets 1,2 and 3 (ARHR1, ARHR2 and ARHR3), are all examples of the FGF23-mediated kind, as is the acquired tumour induced osteomalacia (TIO)." (PMID 29652819, 2018). "Among the identified hypophosphatemic disorders, X-linked hypophosphatemia (XLH) and tumor-induced osteomalacia (TIO) are caused by persistent excess fibroblast growth factor 23 (FGF23), which leads to phosphate renal wasting and reduced phosphate availability." (PMID 41057893, 2025). "X-linked hypophosphatemia (XLH) is the most common heritable form of rickets and results from renal phosphate wasting due to loss of function of PHEX causing excess FGF23, resulting in impaired phosphate reabsorption and ending in hypophosphatemia and decreased conversion of vitamin D." (PMID 37675393, 2023). "X-linked hypophosphatemia (XLH) is caused by inactivating mutations in the phosphate-regulating endopeptidase homolog, X-linked (PHEX) gene, resulting in an excess of circulating intact fibroblast growth factor-23 (iFGF-23) and a waste of renal phosphate." (PMID 34141703, 2021). "However, the tubular maximum reabsorption of phosphate (TmP) per unit GFR (TmP/GFR) did not decrease despite excessive FGF23 secretion in the majority of ADPKD patients, whereas TmP/GFR decreased in X-linked hypophosphatemia patients whose serum FGF23 levels were lower than those in ADPKD patients." (PMID 32178226, 2020).
diabetes (129 papers, 2012 to 2026). "Subsequently, we also found that a higher FGF23 level was associated with a higher risk of developing posttransplant diabetes in a cohort of kidney transplant recipients [61▪]." (PMID 40237064, 2025). "Beyond that, emerging data suggest that deregulated FGF23 contributes to the cardiovascular-kidney-metabolic syndrome through various mechanisms, including the risk of developing diabetes." (PMID 40237064, 2025). "A cross-sectional study involving 403 subjects found that elevated FGF23 levels and the FGF23/Klotho ratio were positively associated with carotid intima-media thickness and carotid atherosclerosis in patients with type 2 diabetes mellitus." (PMID 41426862, 2025). "Of note, more recent studies also point towards a potential role for FGF23 as a risk factor, or potentially even a contributor to, the development of diabetes." (PMID 40237064, 2025). "Recently we found that a higher plasma FGF23 is associated with incident diabetes in the general population." (PMID 38577264, 2024). "Diabetes mellitus: In their observational study, Martin Reindl and colleagues revealed a significant association between diabetes mellitus and FGF23." (PMID 38846254, 2024). "In a first sensitivity analysis, excluding individuals with prediabetes or diabetes at baseline, the highest tertile of FGF23 remained associated with the composite end point incident prediabetes or PTDM." (PMID 38577264, 2024). "Other studies not designed ad hoc for this purpose also showed the existence of an association of FGF23 levels with diabetes." (PMID 34208131, 2021). "Recent studies have associated elevated plasma levels of FGF-23 with a higher prevalence of diabetes mellitus and hypertension." (PMID 33767635, 2021). "Diabetes was associated with FGF23 plasma levels even after adjusting for demographic, clinical, and laboratory data." (PMID 34208131, 2021). "Although the main focus of this review is on FGF23 in diabetes, most data on the association between FGF23 and clinical outcomes are available in patients with CKD." (PMID 32857288, 2020). "In the univariate analyses, all variables except gender (male), presence of diabetes mellitus, urine volume ≥ 100 ml/day, and Log FGF23 were significantly associated with 3-year all-cause mortality (P < 0.05)." (PMID 30977017, 2019). "FGF23 was associated with regulation of serum phosphorus concentration in individuals with diabetes mellitus." (PMID 31581608, 2019). "A total of 422 patients with diabetes mellitus were recruited for this cross-sectional study to examine the association between resistin and intact FGF23." (PMID 30228288, 2018). "Apart from the well-known link between cardiovascular (CV) risk factors, especially diabetes and hypertension, and cerebrovascular damage, elevated FGF23 is also postulated to be associated with cerebrovascular damage independently of CKD." (PMID 30192823, 2018). "Fibroblast growth factor 23 (FGF23) is associated with cardiovascular disease and all-cause mortality in patients with diabetes mellitus." (PMID 30228288, 2018). "Future research is needed to explore the associations between serum FGF23 levels and other complications of diabetes, such as diabetic retinopathy and nephropathy." (PMID 28619026, 2017). "After adjustment for demographic, clinical, and laboratory variables, diabetes remained a significant factor associated with serum FGF23 levels in their study." (PMID 27698482, 2016). "Accumulating evidence supported an association between diabetes and fibroblast growth factor 23 (FGF23)." (PMID 27698482, 2016). "Another study conducted in population with CKD stages 2–4 provided evidence for a positive association between the presence of diabetes and serum FGF23 levels." (PMID 27698482, 2016). "Age, creatinine, Scl levels, FGF23 levels, gender and presence of diabetes were elected for competing risk regression." (PMID 25465028, 2014).
diabetes (continued). "In multivariate analysis, smoking, diabetes mellitus and log FGF23 were each identified as risk factors for CAAC." (PMID 23339433, 2013). "FGF-23 was inversely associated with EF after multivariate adjustment for age, race, gender, diabetes, eGFR, serum C-reactive protein concentrations, LVH, and the use of β-blockers and ACE inhibitors (β –2.03; p = 0.004)." (PMID 23849306, 2013). "Higher serum FGF23 concentrations were associated with older age, higher body mass index, and diabetes in both male and female." (PMID 24015259, 2013). "Adjusted for age and sex, hypertension, diabetes mellitus, smoking, proteinuria, calcium-phosphorus product, and log FGF23 were significantly associated with CAAC." (PMID 23339433, 2013). "Pathophysiology of vascular calcifications in hemodialysis patients is complex and many risk factors such as age, male sex, diabetes and FGF-23 were identified." (PMID 23573501, 2012). "Another route by which FGF23 may contribute to the risk of diabetes is via direct and indirect effects on pancreatic β-cell function." (PMID 40237064, 2025). "Furthermore, higher plasma FGF23 levels have been linked with a higher BMI and insulin resistance in both healthy individuals and patients with diabetes." (PMID 40237064, 2025). "Interestingly, the association between FGF23 and incident diabetes lost significance after additional adjustment for BMI and FGF23 itself was also associated with the development of obesity." (PMID 40237064, 2025). "Future studies should further explore the expression differences of β-Klotho in different populations, ages, obesity degrees and metabolic states, and clarify the value of combined detection of β-Klotho, α-Klotho, FGF23 and other molecules in the risk prediction of diabetes and metabolic syndrome." (PMID 41438297, 2025). "Several studies have shown that FGFs, particularly FGF-2, FGF-19, and FGF-23, are altered in diabetes and may be associated with complications such as nephropathy and impaired wound healing." (PMID 40943671, 2025). "Therefore, the aim of this review is to provide an overview of the present literature on FGF23 as a risk factor for type 2 diabetes, as well as the implications of deregulated FGF23 for cardiovascular risk in patients with diabetes." (PMID 40237064, 2025). "Future research should examine the role of FGF23 in individuals with normal kidney function and explore whether modifying its levels could reduce diabetes and cardiovascular risk." (PMID 40237064, 2025). "Furthermore, mice with a PHEX mutation, leading to FGF23 overexpression, also displayed hyperglycemia and hypoinsulinemia, which are signs of (early) diabetes." (PMID 38577264, 2024). "However, few studies have investigated the association of fibroblast growth factor 23 (FGF23), α-klotho and FGF23/α-klotho ratio with atherosclerosis in patients with type 2 diabetes mellitus (T2DM)." (PMID 38622690, 2024). "Consequently, FGF-23 was suggested as a biomarker to identify persons at risk for diabetes-associated complications." (PMID 36437429, 2023). "Hypertension, diabetes, the deficiency of vitamin D and erythropoietin, proteinuria, high concentrations of fibroblast growth factor 23 (FGF-23), elevated uremic toxins and also the accumulation of advanced glycation end-products (AGEs) are the causes of endothelial dysfunction in CKD." (PMID 36364925, 2022). "The key objective of this study was to determine whether FGF23 may be used as a CV risk factor among patients with long-standing type 2 diabetes mellitus (T2DM)." (PMID 35736431, 2022). "The purpose of this study was to examine the hypothesis that FGF23 may be a potent CV risk factor among patients with long-standing type 2 diabetes mellitus (T2DM)." (PMID 35736431, 2022). "Therefore, we aim to investigate the regulatory effect of 1,25D on Fgf23 and its role in bone metabolism disorder caused by diabetes in vitro and in vivo." (PMID 33609082, 2021).
diabetes (continued). "Positive association between the presence of diabetes and serum FGF23 levels." (PMID 34208131, 2021). "In addition, we investigated the relationship between FGF-23, anti-diabetes therapy and the classic complications and risk factors known to be associated with type 2 diabetes." (PMID 32998751, 2020). "Furthermore, to investigate the association between FGF-23, anti-diabetes therapy and the classic complications and risk factors associated with type 2 diabetes." (PMID 32998751, 2020). "Interestingly, these associations have been observed in patients with reduced and preserved kidney function, highlighting the prominence of FGF23 as a risk factor in patients with diabetes." (PMID 32857288, 2020). "There are some reports that diabetes is associated with FGF23 levels." (PMID 32001956, 2020). "The underlying mechanism via which FGF23 may contribute to LEAD in patients with diabetes remained unclear." (PMID 28619026, 2017). "Dysregulation of the FGF23-Klotho axis contributes to disturbed mineral homeostasis and as such might increase cardiovascular risk in diabetes." (PMID 23945089, 2013). "Another question is whether lowering of FGF23 might reduce the risk of developing diabetes." (PMID 40237064, 2025). "For example, people who had a higher incidence of COVID-19, besides higher levels of plasma FGF23, also were older and had increased rates of diabetes, known risk factors for COVID-19 in the general population and ESRD patients, which may have influenced the differences in clinical outcomes." (PMID 36828412, 2023). "However, a recent study reported that FGF23 and reduced circulating calcifediol were independently associated with non-alcoholic fatty liver disease, perhaps because of its association with insulin resistance and diabetes." (PMID 30909513, 2019). "Since AGEs are increased in diabetes mellitus (DM), our first aim was to evaluate the existence of any potential association between AGEs, FGF-23, inflammation, and increased cardiovascular risk in DM patients on dialysis (CKD-G5D)." (PMID 29147074, 2017). "ANCOVA was applied to compare α-Klotho and FGF-23 levels between groups after adjustment for age, BMI, diabetes, hypertension, asthma, COPD, and thyroid disease." (PMID 41899241, 2026). "This review summarized recent evidence that positions the phosphaturic hormone FGF23 as a potentially important factor in the development of diabetes as well as its cardiovascular complications." (PMID 40237064, 2025). "At the same time, epidemiological studies point towards a role for FGF23 in the development of diabetes." (PMID 40237064, 2025). "Analyzed from the perspective of the year of publication, heterogeneity was higher for age, dialysis treatment duration, diabetes, FGF-23, and hypertension between 2015 and 2020." (PMID 40314886, 2025). "Together, these interactions suggest that sKlotho functions not only as a co-receptor for FGF23 but also as an endocrine modulator that fine−tunes FGFR signaling pathways across multiple organs relevant to diabetes and its complications." (PMID 41438297, 2025). "FGF23 is emerging as a key factor in the cardiovascular-kidney-metabolic syndrome, connecting diabetes and cardiovascular disease." (PMID 40237064, 2025). "Further, FGF23, and GDF-15, were robustly related to PA and have been linked to metabolic disorders such as diabetes or obesity." (PMID 40498722, 2025). "Analyzed from the perspective of the study region, heterogeneity was greater in eastern China for age, SOST, and FGF-23, and in Western China for dialysis treatment duration and diabetes." (PMID 40314886, 2025). "In this study we expand the present knowledge by showing that FGF-23 has a strong association with long-term MACE+ and that this association remains when adjusting not only for age and sex, but also for diabetes, smoking and CKD." (PMID 38524235, 2024).